CD40 (CD40 molecule)
Diseases named in the same sentence as CD40 in open-access papers (continued):
Sharing a sentence is not in itself a finding about the gene and the disease.
tumor (continued). "Among various constitutively- and BCR/CD40-mediated factors secreted, tumour subsets co-express two important immunoregulatory cytokines, IL10 and TGFβ1, both associated with a memory B cell phenotype." (PMID 36973425, 2023). "CD40 is expressed in macrophages, B cells, dendritic cells, and several tumor cells and plays a major role in regulating the anti-tumoral T cell response." (PMID 37895882, 2023). "Agonistic CD40 antibodies have been explored with anti-angiogenic agents in the experimental model, which show that they improved tumor infiltration by cytotoxic T cells." (PMID 36831441, 2023). "Co-expression of Fas-CD40 displayed greatest tumor killing out of all the Fas-TNFRs, with Fas-CD40-19-BBζ-treated mice having significantly lower tumor burden compared with Fas-41BB-19-BBζ (p = 0.0295)." (PMID 37200859, 2023). "Similar to CBT alone, vaccination alone or agonistic CD-40 antibody administration exhibited only a modest response characterized by slowing of tumor growth." (PMID 37548358, 2023). "Consistent with the in vitro results, MC38‐tumor‐infiltrating cDC1 also showed upregulated CD40, CD80, CD86, and MHC‐II expression after RA treatment." (PMID 36876644, 2023). "In stark contrast to the antibodies targeting T cell immunomodulatory receptors, agonist anti-CD40 markedly improved tumor regression in mice treated with RT+CTLA4i." (PMID 37620372, 2023). "Following rigorous validation, the CD40 antibody clone EPR20540 was used to screen a variety of solid tumor types for CD40 expression on the tumor." (PMID 36894898, 2023). "This indicates that intratumoral CD40 delivery can polarize macrophages locally toward a pro‐inflammatory M1 phenotype, possibly aiding with suppression of tumor growth." (PMID 36658712, 2023). "This CD40 tumor expression showed marked heterogeneity between different cores of the same tumor, and partial correlation between the expression of CD40 by tumor cells and the expression of CD40 by stromal cells." (PMID 36894898, 2023). "Here, we employed quantitative immunofluorescence (QIF) to assess the expression levels of CD40 in several tumor types." (PMID 36894898, 2023). "An ideal agonist mAb can lead to CD40 crosslinking to promote greatest agonist and anti-tumor activities with minimal adverse events." (PMID 37215135, 2023). "In agreement, treatment with agonistic CD40 antibodies dampened tumor growth more efficiently in Vegfr2Y1173F/+ mice compared with WT mice." (PMID 37651195, 2023). "Nonetheless, CD40 activation via agonists are an important strategy for altering macrophages to acquire an M1 phenotype that is anti-tumor." (PMID 37693009, 2023). "The switching of M2 to M1 involves signaling associated with CD86, CD80, CD40, IL-12, IL-6, and TNF-α ensuing in enhanced antigen uptake by the macrophages and activation of T cells-mediated mice tumor growth regulation." (PMID 37936697, 2023). "In contrast, agonistic CD40 therapy leads to deep and complete tumor responses in a majority of 4T1 tumor-bearing mice, an effect that is confirmed in the AT3 tumor model." (PMID 37620372, 2023). "After the ligation of CD40 expressed on antigen-presenting cell, such as macrophages, dendritic cells, and B cells, anti-CD40 leads to the activation of these cells, enhances antigen presentation, and induces an effective T cell anti-tumor response." (PMID 37342258, 2023). "Conversely, NDES delivered CD40 mAb showed the addition of radiation therapy significantly enhanced the tumor reduction." (PMID 36658712, 2023). "RA‐treated B16‐OVA tumor cells markedly increased the surface expression of activation markers, including CD40, CD80, CD86, MHC‐I, and MHC‐II on BMDCs." (PMID 36876644, 2023). "In a prophylactic in vivo study, CD40-humanized transgenic mice vaccinated with nano-AAM/CD40 demonstrated complete prevention of tumor growth when challenged with MC38 tumor cells in 50% of the mice for up to 80 days." (PMID 37946275, 2023).
tumor (continued). "The anti-tumor effect of agonistic anti-CD40 is both T-cell-driven and T-cell-independent, driven through reprogrammed anti-tumor macrophages." (PMID 38140118, 2023). "CD40-targeting therapies can enhance the dendritic cell priming of tumor-specific T cells and repolarize intratumoral macrophages to alleviate the tumoral immunosuppressive environment and remodel the extracellular matrix." (PMID 37830579, 2023). "CD40 is broadly expressed by immune, hematopoietic, vascular, epithelial, and other cells, including a wide range of tumor cells." (PMID 37085653, 2023). "The frequency of tumor cells expressing apical Cxcl9/Cxcl10 was significantly decreased in KPC recipients of 1045 T cells or 1045 T cells + CD40 agonist." (PMID 36472588, 2023). "In patients with PDAC, combined treatment with CD40 agonist (CP-870,893) and gemcitabine led to a reduction in tumor burden in phase I study (NCT00711191)." (PMID 37771596, 2023). "In stark contrast, the triple combination of CBT with therapeutic vaccination and a single dose of agonistic CD40 antibody induced complete tumor control in three of five (60%) mice and a significant delay in tumor growth in the remaining 40% of mice." (PMID 37548358, 2023). "In the tumor microenvironment, activation of macrophages through CD40 ligation promotes tumor restriction and is being considered clinically." (PMID 39872733, 2023). "Publicly available TCGA data on CD40 mRNA expression were also analyzed in the same tumor types that were assessed for protein expression by QIF." (PMID 36894898, 2023). "Recently, sequential intravenous administration of FLT3L or CD40 agonist has been shown to activate tumour-resident cDC1s in tumour-bearing mice." (PMID 37433774, 2023). "CD40 is expressed by various cells, including B cells, monocytes, DCs, fibroblasts, tumor cells and ECs." (PMID 37666809, 2023). "focused on stimulating neutrophils with TNF‐α and anti‐CD40 antibody and examining anti‐tumor killing by ADCC via tumor‐binding antibodies." (PMID 38062888, 2023). "The high percentage of tumor cells expressing CD40 in each of these solid tumors should be considered in the development of therapeutic agents designed to target CD40." (PMID 36894898, 2023). "Panc02 tumor‐bearing mice were randomized into treatment groups, UnTx, IP CD40, NDES CD40, Rad only, Rad + IP CD40, and Rad + NDES CD40." (PMID 36658712, 2023). "The cell-surface molecule CD40, a member of the tumor necrosis factor receptor superfamily, broadly regulates immune activation and mediates tumor apoptosis." (PMID 37409273, 2023). "Activated GC B cell genes like CD83 and CD40 were highly expressed in tumour‐free TDLN, whereas the expression level of immature B cell markers like CD27 was higher in PT." (PMID 37491740, 2023). "The marked improvement in tumor rejection achieved with anti-CD40 suggested a critical role for increased antigen cross-presentation and T-cell activation in this response." (PMID 37620372, 2023). "Previous studies have demonstrated that CD40 stimulation can remodel the tumor microenvironment in a manner that promotes effector immune cell responses and can cooperate with immune checkpoint inhibition for durable tumor control mediated by T cells." (PMID 37123403, 2023). "Genetic inactivation of PPARδ in B cells impaired the development and function of IL-10+ B cells, and treatment with PPARδ inhibitor diminished the induction of IL-10+ Bregs by tumor and CD40 engagement." (PMID 37291146, 2023). "New drug delivery approaches that can leverage the anti-tumor activity of anti-CD40 but minimize toxicity are needed." (PMID 38140118, 2023). "The influence of the CD40/CD40L axis extends far beyond its impact on the tumor vasculature and leukocyte trafficking, as it also modulates the activities of many other cellular components in the TME." (PMID 37810959, 2023).
tumor (continued). "Differently, the expression of critical immune regulators, namely PD-L1 and the M1 marker CD40, on monocytes/macrophages in our tumor spheroids depended on their co-culture with PANC-1 cells and PSC." (PMID 37519820, 2023). "CD40L expression on CAR-T cells resulted in elevated surface expression of costimulatory molecules, adhesion molecules, HLA molecules and Fas death receptor on CD40+ tumor cells, thus increasing their immunogenicity." (PMID 37509328, 2023). "The combination of anti-PD-1 antibody and anti-CD40 agonistic antibody significantly reduced tumor growth compared to the IgG control, and to anti-PD-1 and anti-CD40 as monotherapies in subcutaneous, orthotopic and two plasmid-based murine iCCA models." (PMID 36980187, 2023). "Recently, a cocktail consisting of TNFα, CD40 agonist and a tumour-specific antibody was shown to increase the ability of neutrophils to kill human tumour cells in vitro." (PMID 37180120, 2023). "In contrast, treatment with an agonistic CD40 Ab resulted in tumor responses in the majority of tumor-bearing mice, an effect that was dependent on CD8+ T cells." (PMID 37872395, 2023). "CD4+ T cells are necessary to build a humoral response against tumor Ags by providing help via CD40 ligand signaling to CD40 on B cells to drive their differentiation and maturation into affinity-matured, class-switched plasma cells." (PMID 36719372, 2023). "When the anti-PD-1 antibody was combined with CD40 ab, it resulted in decreased tumor burden in mice when compared to the single antibody treatment." (PMID 36769180, 2023). "In cancer immunotherapy, through the binding with agonist mAbs, CD40 can stimulate T cells and APCs to attack tumor cells." (PMID 37215135, 2023). "Agonism of CD40 has been shown to activate cross-presenting dendritic cells, re-educate tumor macrophages toward an M1 phenotype, decrease collagen deposition in the tumor stroma, and trigger antitumor T cell responses." (PMID 37568782, 2023). "The pharmacodynamic effects of mitazalimab have been preclinically evaluated in tumor-bearing human CD40-transgenic mice." (PMID 37830579, 2023). "CD40/CD40L interaction in vivo produces a direct cytotoxic effect on CD40-expressing tumor cells and further circumvents tumor immune escape." (PMID 36797756, 2023). "All of three of these cancer types displayed considerable intra-tumoral heterogeneity of CD40 expression, as well as partial correlation between expression of CD40 on tumor cells and on surrounding stromal cells." (PMID 36894898, 2023). "In some murine tumor models, the antitumor activity of agonistic CD40 antibodies is T cell-dependent." (PMID 38008741, 2023). "CD4+ T cells also induce humoral responses to tumor antigens on B cells through the interaction of CD40 with CD40 ligands." (PMID 37033978, 2023). "PDL1 blockade and/or activation of CD40 or 4-1BB pathways into the TME are proven effective ways to enhance the anti-tumor immune response, particularly in combination with OV treatment." (PMID 38053848, 2023). "TAM that express CD40 can switch their activities from immunosuppression to tumor killing after interaction with CD40L+ T cells that secrete Th1 cytokines." (PMID 37810959, 2023). "CD40 activation leads to an increase in CCL5 expression by TAMs allowing the recruitment of CD4+ T cells into the tumor, which are essential for tumor regression." (PMID 37143666, 2023). "Through Tim-3/galectin-9 (Gal-9) and CD40L/CD40 axes, tumor-induced senescent T cells interact with Mo/Ma, participating in the latter’s canonical activation and thus indirectly facilitating angiogenesis." (PMID 37046588, 2023). "For example, CD40L is expressed on T cells, and its interaction with its receptor can lead to the activation of APCs and the apoptosis of CD40+ tumor cells." (PMID 37509328, 2023).
tumor (continued). "CD40 activation has been shown to stimulate productive T cell immune surveillance in cancer leading to inhibition of tumor growth as seen in animal models as well as in some patients." (PMID 37693009, 2023). "Here the authors provide immunological insights into the response to RT and CTLA4 inhibition in tumor bearing mice and show that agonistic CD40 therapy improves response to the combination of RT and immune checkpoint inhibition." (PMID 37620372, 2023). "CAR-T cells expressing CD40 ligand (CD40L) can not only directly enhance the killing of CD40-positive tumor cells but also activate APCs and mobilize other endogenous immune cells to participate in anti-tumor responses and avoid tumor immune escape." (PMID 37596653, 2023). "CD40-activated macrophages quickly invaded tumors, were tumoricidal, and aided the removal of tumor stroma." (PMID 37426676, 2023). "And there are some developing drugs to reprogram TAMs from a pro-tumor phenotype to an anti-tumor phenotype and interrupt the bad cycle between TAMs and tumor cells, such as agonistic anti-CD40 antibodies, PI3Kγ inhibitors." (PMID 35967444, 2022). "CD40 agonists can also polarize macrophages in the tumor microenvironment to adopt a pro-inflammatory state that can kill tumors in preclinical studies." (PMID 36143975, 2022). "This key process was modulated by engagement of CD1d, first apoptosis signal receptor (FAS), and CD40 molecules and, of note, iNKT cell transfer into tumor-bearing mice resulted in tumor growth inhibition and decreased M2-like TAMs." (PMID 36338516, 2022). "CD40 signaling in cDC1 is required for tumor rejection by playing a key role in augmenting the proliferation of antigen-specific CD8+ T cells." (PMID 36311701, 2022). "Accordingly, hyperacetylation/upregulation of oncogenes related with angiogenesis and vascular invasion (COL24A1, NDP and HOXA13) and hypoacetylation/downregulation of angiogenesis-tumor suppressor genes (CD40 and IL15) was identified in this study." (PMID 35740301, 2022). "We observed that tumor-infiltrating cDC1s, cDC2s, slanDCs and moDCs obtained from dex-treated patients showed a lower expression of HLA-DR and CD40 compared with untreated patients." (PMID 36703985, 2022). "Since HL cells express high levels of CD40, it is likely that they are continuously stimulated by ligand expressing cells from the tumor microenvironment and thus receive a long-lasting CD40-signal similar to LMP1/CD40-expressing B cells." (PMID 36110848, 2022). "If that is the case, exogenous CD3 ligation and CD40 signaling can complement/boost tumor-reactive T cell reactivation in the presence of tumor antigen." (PMID 36073543, 2022). "We identified at least five promising treatment strategies, of which the panobinostat, venetoclax and anti-CD40 triple therapy was the most effective in inducing complete tumor remission across models." (PMID 35788566, 2022). "CD40 activates macrophages to infiltrate rapidly around the tumor cells, weaken the immunosuppressive effect in the TME and drive T cells to produce anti-tumor responses." (PMID 35493517, 2022). "In contrast to agonist therapy, increasing the CD40/CD40L interaction between tumor cells and macrophages is also a promising treatment for cancer." (PMID 36497444, 2022). "Taken together, these studies indicate that CD40-activated B cells can express, process and present antigens on both MHCI and MHCII when transduced with tumor antigen encoded by DNA or RNA." (PMID 36159874, 2022). "LVGN7409 activates CD40 signaling in Fc-FcγRIIB cross-link dependent manner and thus operates optimally in a CD40 and FcγRIIB-enriched tumor microenvironment." (PMID 35865955, 2022). "Additional CD40 agonist drugs purported to have improved designs for anti-tumor activity continue to be developed." (PMID 36077755, 2022). "Mechanistically, MSLCs are reprogrammed by the CD40L/CD40/NFκB2 signalling axis to build a tumour infiltrative microenvironment involving collagen crosslinking." (PMID 35908277, 2022).
tumor (continued). "CD40 agonist promotes the accumulation of the functional intratumoral Klrg1+ subset in PDA in wild-type tumor-bearing mice." (PMID 35393950, 2022). "NK cells in tumor bearing mice express elevated levels of CD40L, and interactions with CD40 cause increased APC maturation." (PMID 36531040, 2022). "Prior studies suggest Batf3 is required for antitumor activity when CD40 agonist is used in combination with chemotherapy and immune checkpoint blockade, for the most part in subcutaneous tumor models." (PMID 35393950, 2022). "The capacity to induce tumour-cell specific apoptosis represents the most unique feature of the TNF receptor (TNFR) family member CD40." (PMID 36291141, 2022). "Starting 2 d after treatment, there was a significant increase in the proportion of converted tumor-migratory CD103+ cDC1s co-expressing CD40 and CD80 in the radiation-treated group compared with untreated controls." (PMID 35487695, 2022). "CD40 is normally expressed on antigen-presenting cells (APC) or macrophages, and CD40 agonists (CD40a) can activate maturation of APCs for enhancing tumor-specific antigen presentation." (PMID 36298450, 2022). "Tumor cell-derived CCL2 decreased M1-like phenotype of TAMs via ZC3H12A-TRAF6/3 signaling, whereas CD40 markedly protected the TRAF6/3 from K63-linked deubiquitination, thereby reactivating the NF-κB signaling." (PMID 35851310, 2022). "CD79A/CD40 co-stimulated CAR-T cells also had superior anti-tumor activity and proliferative activity compared to CD28 or 4-1BB co-stimulated CAR-T cells in mice inoculated with Raji tumor cells." (PMID 35053463, 2022). "Our results show that M1 TAM in KC-HPC-API mice exhibit upregulation of CD40, which corresponded with an increase in their production of iNOS and coincided with tumor regression." (PMID 35892872, 2022). "The proportion of CD11c+CD40+ tumor‐infiltrating DCs in PNVAC+ISA 51 group was 1.60‐fold higher than that in free vaccine‐treated group (free vaccine+ISA 51 vs PNVAC+ISA 51: 42.87 vs 68.67, P < 0.001)." (PMID 36351249, 2022). "Activated macrophages with CD40 agonist invaded tumors immediately, were tumoricidal, and aided tumor stroma elimination." (PMID 36303138, 2022). "We also highlight therapeutic advancements targeting the CD40 system to either attenuate the neuroinflammatory response or leverage the downstream effects of CD40 signaling for direct tumor cell lysis." (PMID 35456932, 2022). "Because of these limitations, only a handful of tumor surface antigens have thus far been identified as suitable targets for CD40 bispecific antibodies." (PMID 35911742, 2022). "Low expression levels of CD40 on DCs support tumor growth, in contrast high expression levels induce tumor-regressing T cell responses." (PMID 36230990, 2022). "The artificial expression of CD40L on the surface of any tumor-targeted CAR-T cell further provides an additional interesting opportunity to exploit CD40/CD40L signaling to stimulate endogenous anti-cancer T cell immunity." (PMID 35053463, 2022). "Preclinical models using agonistic anti-CD40 mAb have shown secondary T cell activation and tumor regression." (PMID 36230990, 2022). "Using an orthotopic Pan02 tumor mouse model, combining the CD40 agonist (3 mg/kg on day 7, 14, 21, 28; clone FGK4.5) with PD-L1 blockade (10 mg/kg on day 7, 10, 14, 17, 21, 24; clone 10F.9G2) improved OS versus monotherapy with either agent." (PMID 35139879, 2022). "More commonly, the ability of CD40 stimulation to control tumors has been performed with the addition of tumor-derived antigen." (PMID 34282297, 2022). "In a murine model of this cancer, a monoclonal anti-CD40 agonist antibody is able to induce tumor regression by repolarizing macrophages toward a pro-inflammatory phenotype." (PMID 35214076, 2022).